IL6 (interleukin 6)
Diseases named in the same sentence as IL6 in open-access papers (continued):
Sharing a sentence is not in itself a finding about the gene and the disease.
COVID-19 (continued). "This test highlighted significant differences between the three groups of COVID-19 severity in IL-6 concentrations, CRP, % neutrophils, lymphocyte count, % lymphocytes, eosinophil count, % eosinophils, NLR, PLR, and urea." (PMID 36838284, 2023). "AMP, along with the daily practice of SKY, during normal life (pre-COVID-19 phase) reduced mRNA expression of IL1β, IL6, and TNF and increased mRNA expression of SOD, catalase, and GPx." (PMID 37546047, 2023). "The current study also assessed the relationship of polymorphisms of the cytokine genes IL2, IL6, and IL10 with the severity of COVID-19 in Kazakh population." (PMID 37390087, 2023). "Further molecular docking revealed that quercetin has a higher affinity for IL6 and IL10 in the TNF signaling pathway associated with COVID-19." (PMID 38050310, 2023). "Panels A, C show the distribution of SeptiScores across varying COVID-19 severities, whereas Panels B, D show the IL-6 levels in pg/ml for patients across the same clinical severities." (PMID 36653401, 2023). "Several investigations have shown that IL-1 regulates the production of IL-6, one of the primary unfavorable prognostic markers in COVID-19." (PMID 36902537, 2023). "The aim of this study is to explore the role of IL6 in predicting outcome in critically ill COVID-19 patients." (PMID 36857362, 2023). "Distinct serum cytokine profiles are observed in association with COVID-19 severity, with the most severe patients having elevated levels of TNF-α, IL-6, IL-8, and IL-10." (PMID 37111341, 2023). "Another clinical study also showed increased levels of IL-6 and IL-10 amongst 32 COVID-19 patients who are now deceased due to SARS-CoV-2 infection compared to those who survived." (PMID 37457959, 2023). "Further, the use of the IL-6 inhibitor Tocilizumab is now known to improve survival in hospitalised severe COVID-19 patients with systemic inflammation." (PMID 37063871, 2023). "A controlled cohort study (NCT04322188) evaluated the impact of siltuximab, a monoclonal antibody against IL-6, on the mortality rate of 30 COVID-19 patients requiring ventilator support." (PMID 36793739, 2023). "In COVID-19, IL-6 has been characterized as an indicator of cytokine release syndrome and thus a prognostic marker for the clinical outcome." (PMID 37733154, 2023). "A new yttrium metal–organic framework has been synthesized and functionalized with a specific DNA sequence to perform the selective ratiometric luminescence sensing of IL-6 and oseltamivir that are important COVID-19 biomarker and potential drug." (PMID 37234896, 2023). "In fact, transcript levels for the pro-inflammatory cytokines TNF-α, IL-6, and MMP8 in biopsies from COVID-19-associated AKI patients were comparable to those found in normal controls." (PMID 36979824, 2023). "One retrospective study described IL-6 as an independent predictor for COVID-19 lung injury, measured semi-quantitatively." (PMID 37733154, 2023). "IL-6 is a pleiotropic cytokine that has emerged as a key driver of inflammatory responses and disease severity in COVID-19." (PMID 38090572, 2023). "This assumption is confirmed by evidence from clinical trials investigating the efficacy of anti-IL-6 drugs in patients with severe COVID-19." (PMID 37371775, 2023). "A single-cell sequencing of alveolar epithelial cells showed that SARS-CoV-2 induced IL-6 expression, and IL-6 has widely been acknowledged to play an important role in COVID-19." (PMID 37376572, 2023). "The acute coronary syndrome has also been shown to be more prevalent in patients with COVID-19, and that is likely due to the overall proinflammatory state, as IL-6 has been shown to promote vascular inflammation." (PMID 37273379, 2023). "A similar association was previously reported by our group where we identified elevated serum levels of IL-6 and granzyme B to predict liver injury in COVID-19 patients." (PMID 36902854, 2023).
COVID-19 (continued). "In another study, high levels of inflammatory markers such as CRP, erythrocyte sedimentation rate, IL-6, and procalcitonin in COVID-19 patients were reported to indicate hyperinflammatory reactions in COVID-19 patients." (PMID 36919085, 2023). "Multiple inflammatory factors are significantly increased in COVID-19 patients, such as interleukin-6 (IL-6), tumor necrosis factor-α (TNF-α), and C-reactive protein (CRP)." (PMID 37583958, 2023). "Of the analyzed pro-inflammatory cytokines, the concentrations of interleukin (IL)-1β, monocyte chemotactic protein 1 (MCP-1), IL-6, IL-8 and IL-17A were significantly higher in severe COVID-19 patients compared to healthy controls." (PMID 36851312, 2023). "Currently, both inhibitors of both IL-β1 and IL-6 pathways were approved for the treatment of hospitalized severe COVID-19 patients." (PMID 36941580, 2023). "SARS-CoV-2 maternal infections display higher frequencies of CXCR5+CD4+ and CCR6+CD4+ T cells and higher plasma concentrations of IL-6 and IL-18, when compared with gestational age–matched COVID-19–vaccinated counterparts." (PMID 37490342, 2023). "Inhibitors of janus kinase (JAK) block the intracellular signalling pathways of cytokines that promote and sustain inflammation in severe COVID-19, including IL-2, IL-6, IL-10, GM-CSF and IFNγ." (PMID 36941580, 2023). "Amongst those with acute COVID-19, eleven markers significantly differed across disease severity categories: IL-1β, IL-2, IL-6, IL-10, IL-18, IL-23, IL-33, TNF-α, IP-10, G-CSF and YKL-40." (PMID 37063871, 2023). "IL-6 and TNF-α that are robustly high during COVID-19 have been linked to reduced BMPR2 expression and associated with severe disease and death in patients with pulmonary arterial hypertension (PAH)." (PMID 36634048, 2023). "Conclusion: sRAGE concentrations, but also Il10 and Il6/mHLA DR ratio seemed interesting to predict the risks of intubation and death in critically ill COVID-19 patients." (PMID 37311846, 2023). "The median (min–max) IL-6 levels for mild and severe COVID-19 were 3.59 (1.50–638.30) pg/mL and 28.82 (5.52–926.30) pg/mL, respectively (p <0.001)." (PMID 38099004, 2023). "While there are contrasting findings on the role of IL-6 in pediatric COVID-19, in adults, IL-6 has been reported to be a relatively good predictor of disease severity." (PMID 37047752, 2023). "Clinical studies have shown abnormal concentrations of different relevant cytokines in patients with COVID-19, such as IL-6, TNF-α, IL-1β." (PMID 38018195, 2023). "As well, in a prospective study, PTX inhibits COVID-19 severity by reduction of IL-6 and c-reactive protein (CRP) and improved prognosis of patients when combined with antioxidants." (PMID 36850013, 2023). "The levels of all analyzed interleukins, including TNF, IL-6, IL-1B, IL-8, IL-10, and IL-12p70, were significantly higher in the COVID-19 group compared to the control group." (PMID 37373613, 2023). "The protein–protein interaction network corresponding to these differentially expressed cytokines/chemokines identifies sIL2R->IL6->IP-10->IL-10->MIG as the network path with the highest inflammation in MIS-C relative to COVID-19." (PMID 37685502, 2023). "Inflammation-related soluble blood markers such as IL-6 have been consistently described as a marker for COVID-19 severity." (PMID 37112998, 2023). "The efficacy of tocilizumab, a recombinant monoclonal antibody against IL-6, was tested in severe COVID-19 patients, but with discordant results, either a significant reduction in ventilation dependency or without efficacy." (PMID 38068297, 2023). "It was also mentioned that patients with COVID-19 receiving intensive care unit treatment have higher fatality rates when their IL-6 levels are high." (PMID 37927596, 2023). "The hsa-miR-146a-5p increase we observed in post-COVID-19 patients is an indication of the path to recovery, as the levels of IL-1, IL-6 and TNF-α cytokines are inversely correlated to has-miR-146a production." (PMID 38110483, 2023).
COVID-19 (continued). "It is important to note that IL-6 is a key inflammatory mediator in autoimmune inflammation and cytokine storms, and its high expression is correlated with the severity of COVID-19 and mortality." (PMID 37163438, 2023). "Available evidence has verified that COVID-19 patients had increased serum levels of proinflammatory cytokines, such as IL-1β, IL-6 and IL-10, alluding to the implication of a cytokine storm." (PMID 37251383, 2023). "The results demonstrated that patients with COVID-19 presented elevated levels of IL-6, lymphocytopenia, and delayed cytotoxic immune defense." (PMID 37408184, 2023). "Long COVID-19 patients had higher mean IL-6 levels than healthy individuals (mean difference = 9.75 pg/ml, 95% CI = 5.75–13.75 pg/ml, I2 = 100%, P < 0.00001)." (PMID 37095536, 2023). "IL-6 levels are increased in COVID-19 patients as part of the cytokine storm and have been considered as a biomarker for disease severity." (PMID 38003837, 2023). "Elevated necrosis factor alpha (TNF-α), interleukin-1 (IL-1), IL-6, levels have been reported in severe COVID-19." (PMID 37712090, 2023). "Patients with positivity for aPI IgM had higher acute inflammatory marker IL-6 levels, and those with positivity for aPS IgM showed a higher occurrence of thrombosis during their hospitalisation for COVID-19." (PMID 37626797, 2023). "Elevated concentrations of immune-derived markers of systemic inflammation, such as tumour necrosis factor-α (TNF-α), interleukin-6 (IL-6) and interleukin-8 (IL-8), have been observed up to 40 days after COVID-19." (PMID 36703183, 2023). "VD levels are related to decreased levels of interleukin-6, which plays a part in the cytokine storm found among critically ill individuals and is related to a poorer COVID-19 prognosis." (PMID 38161941, 2023). "The results of recent research indicate that the active forms of vitamin D have anti-inflammatory effects in COVID-19 by inhibiting interleukin (IL)-1, IL-6, IL-17, tumor necrosis factor-α, and interferon-γ." (PMID 37109161, 2023). "Aside from predicting the severity of COVID-19, IL-6 is also utilized as a biomarker to predict various diseases." (PMID 36679421, 2023). "Persistently elevated inflammatory markers (IL-6 and CRP) were risk factors for unfavorable outcomes, while low serum anti-S1/S2 IgG and ambulatory acute COVID-19 correlated with better recovery." (PMID 37893068, 2023). "During COVID-19, IL-6 inhibitors were less prescribed (48 (21%) vs. 21 (10%) prescriptions, p = 0.003), while IL-17A inhibitors were more prescribed (39 (17%) vs. 61 (30%) prescriptions, p = 0.001)." (PMID 37623450, 2023). "C-reactive protein (CRP), interleukin-6 (IL-6), neopterin, Kyn, Phe concentrations were significantly increased, and Trp levels depleted during acute COVID-19." (PMID 37038445, 2023). "Clinical evidence suggests that patients with severe COVID-19 have markedly increased levels of pro-inflammatory cytokines within their bodies, including IL-1β, IL-2, IL-6, IL-7, IL8, TNF-α, CCL2, MIP-1α, and CXCL10." (PMID 37163438, 2023). "COVID-19 patients with increased IL-6, D-dimer, and ferritin levels receiving antibiotic treatment were more likely to show dysbiosis with increased abundance of Enterococcus." (PMID 37373960, 2023). "There was a slight positive correlation between IL-6 levels in COVID-19 patients and CRP, fibrinogen, and procalcitonin levels (RS = 0.25, P value .001), (RS = 0.31, P value .001), and (RS = 0.24, P value .001)." (PMID 37960722, 2023). "Severe COVID-19 patients had elevated levels of cytokines, IL-6, CXCL-10, and HGF compared to mild/moderate." (PMID 37685858, 2023). "It is noteworthy that the serum levels of IL-6 in patients with COVID-19 are positively correlated with the severity of the disease." (PMID 37112918, 2023).
COVID-19 (continued). "Based on our results, we recommend that oligosymptomatic MIS-C patients or those suspected of long COVID-19, with elevated IL-6 and other inflammatory activity, should be screened for possible cardiological involvement." (PMID 38138278, 2023). "In our study, proteomic analysis (Olink assay) of individuals with COVID-19 also confirmed significantly increased protein abundance of IL-6." (PMID 37832397, 2023). "Increased IL-6 levels and hyperferritinemia are regarded as markers of systemic inflammation and an unfavorable prognosis in COVID-19." (PMID 38005862, 2023). "The use of antivirals, corticosteroids, and IL-6 inhibitors has been recommended by the WHO to treat COVID-19." (PMID 37374049, 2023). "Pro-inflammatory IL-6 participates in the hyperinflammatory response during COVID-19 infection and has a prolonged normalization in post-COVID-19 patients." (PMID 37896963, 2023). "We examined possible relations of cluster membership with clinical outcomes through regression analysis, thereby correcting for age, gender, BMI and interleukin-6 (IL-6) levels, which are reported to relate to outcome in COVID-19." (PMID 37582864, 2023). "TNF-α, IFN-γ, and IL-6 represent vital inflammatory mediators in the progression of lung injury in both sepsis and COVID-19 scenarios." (PMID 37822934, 2023). "Plasma IL-6 concentrations were measured on 191 COVID-19 patients using the Roche Elecsys IL-6 assay on the Cobas immunoassay analyzer and the Meso Scale Discovery (MSD) assay." (PMID 37650680, 2023). "The highly expressed cytokines in COVID-19 patients included IL-10, IL-6, IL-7, TNF-α, IFN-α, CCL2, and CCL4, but only incubation monocytes with IL-10 downregulated HLA-DR expression." (PMID 36834656, 2023). "The concept of interleukin inhibition has been refined in the context of COVID-19 with the IL-6 inhibitor tocilizumab being one of the first established treatment options for COVID-19." (PMID 36769623, 2023). "COVID-19 patients supplemented with vitamin K2 had reductions in IL-6 and tumor necrosis factor-alpha (TNFα) expression." (PMID 36831641, 2023). "Convalescent COVID-19 subjects of the study group (rehabilitation) with increased serum levels of circulating IL-6 had a greater reduction in FMD." (PMID 36983234, 2023). "The administration of dexamethasone to critical COVID-19 patients was found to significantly reduce the plasma levels of inflammatory mediators including IL-1β, IL-6, IL-8, IL-10, and MIP-1α, and this to counteracted hyper-inflammation." (PMID 37631998, 2023). "Interleukin 6 (IL-6) levels in mild and moderate COVID-19 patients with the type (quantitative or qualitative) of taste disorders were compared in this observational study." (PMID 35801415, 2023). "The patient cohorts, i.e., the whole cohort and the subgroup of COVID-19 patients, had higher plasma IL-6 levels than the controls." (PMID 38139346, 2023). "Among the different pro-inflammatory responses triggered by SARS-CoV-2 infection, IL-6 has been shown to be consistently elevated in the blood of severe COVID-19 patients and can induce HSPCs and human primary monocytes to develop into MDSC-like cells." (PMID 38257728, 2023). "IL-6 showed in both groups a significant correlation with pulmonary infiltrates (COVID-19: ρ = 0.65, p < 0.001; non-COVID-19: ρ = 0.60, p < 0.05)." (PMID 37733154, 2023). "Targeting this pathway, the use of the IL-6 inhibitor, tocilizumab, resulted in a reduction in clinical endpoints in hospitalized patients with COVID-19." (PMID 36769623, 2023). "To determine the pro-inflammatory effects of S1 spike protein on BEAS-2B and A549 cells, we measured the levels of IL-1β, TNF-α, IL-6, and IL-8, crucial inflammatory cytokines in COVID-19." (PMID 37834316, 2023). "Cytokines (IL-2R, IL-6, IL-8, TNF-α, and IL-10) were significantly associated with in-hospital mortality in COVID-19 patients." (PMID 37735372, 2023).
COVID-19 (continued). "Studies describing the immunological profile of critically ill COVID-19 patients suggest hyperactivation of the humoral immune pathway Interleukin6 (IL6)." (PMID 36857362, 2023). "A subsequent study by these researchers aimed at identifying a “window of therapeutic opportunity” for enhancing IL-6 blockage effectiveness in COVID-19." (PMID 37759738, 2023). "IL-6 levels above 35 pg/ml have been used to ascertain the need for mechanical ventilation in COVID-19 patients." (PMID 36653401, 2023). "The IL-6 level was increased in mild COVID-19 patients and was significantly elevated in severe COVID-19 patients." (PMID 37363608, 2023). "In other studies, the severity of COVID-19 can be predicted by using the optimal threshold of IL-6 over 24.3 pg/mL or 26.09 pg/mL." (PMID 36679421, 2023). "Plasma IL‐6 is a potential prognosis factors in COVID-19 severe patients and a vital factors between endothelial cells and neutrophils." (PMID 37553691, 2023). "Only patients with COVID-19 received IL-6 or Il 1 receptor antagonist treatments, 4.8% vs 0% (p < 0.01), respectively." (PMID 37902869, 2023). "Transcripts of genes encoding 6 biomarkers, IL-1β, IL-6, IL-10, C-reactive protein, IDO1 and ACE2, were measured by RT‒qPCR in saliva samples of patients and COVID-19-free individuals." (PMID 37715121, 2023). "Among these, IL-6 levels have been shown to correlate with the severity of COVID-19 patient outcomes." (PMID 38030681, 2023). "It has been previously demonstrated that the levels of IL-6 correlate with COVID-19 severity, while miR-146a-5p is a negative regulator of NF-κΒ, which is in turn a transcription factor of the gene encoding IL-6." (PMID 36768701, 2023). "It is well established that during the acute phase of the disease, some COVID-19 patients display higher levels of several classical pro-inflammatory cytokines, including IL-6, IFNa and TNF." (PMID 37700317, 2023). "IL-6 inhibitors, such as tocilizumab and sarilumab, have been used in clinical trials to reduce inflammation and improve outcomes in COVID-19 patients." (PMID 37649897, 2023). "For instance, increased IL-6 levels in circulating were tested in patients with cardiovascular conditions with a poor prognosis of COVID-19." (PMID 37033622, 2023). "In other cases, blood levels of GM-CSF and M-CSF were significantly heightened in severe COVID-19 patients and a combinatorial treatment of HSPCs with IL-6, GM-CSF, and M-CSF enhanced the generation of MDSC-like cells." (PMID 38257728, 2023). "For example, Liu and colleagues reported a 67.9% increase in IL-6 in patients with COVID-19 and found that levels of IL-6 and C-reactive protein (CRP, a biomarker of inflammation) in the severe group was significantly higher than in the mild group." (PMID 36983445, 2023). "Considering the presence of cytokine storm and inflammatory response in sepsis and coagulopathy of COVID-19 patients, IL-6 is identified as a potential drug target." (PMID 38094124, 2023). "IL-6 has also been implicated as the cause of cytokine release syndrome in SARS-CoV-2 infection, and hence the use of IL-6 inhibitors tocilizumab for the management of severe COVID-19." (PMID 36482706, 2023). "The ongoing clinical trials are investigating potential of repurposing FDA-approved IL-6 inhibitors: siltuximab, sarilumab and tocilizumab for COVID-19 treatment." (PMID 37051070, 2023). "Serum ferritin levels are increased in COVID-19 due to inflammation and the release of cytokines, particularly IL-6, that stimulate hepcidin synthesis, a master regulator of iron uptake and distribution." (PMID 37565145, 2023). "Some proinflammatory markers that are elevated during severe COVID-19 include IL-6, IL-8, IL-1β, TNF-α, MCP-3, TGF-β, CXCL10 and IL-17, amongst others." (PMID 37153606, 2023). "Supplementation of the post-COVID-19 serum with NAC or Sulodexide reduced the synthesis of IL-6 to −18%, p < 0.02 and −24%, p < 0.01, respectively." (PMID 38188630, 2023).